INSR (insulin receptor)
Diseases named in the same sentence as INSR in open-access papers (continued):
Sharing a sentence is not in itself a finding about the gene and the disease.
Insulin resistance (continued). "It is presumed that heterozygous mutations in INSR lead to both insulin resistance and hypoglycemia through tissue-specific insulin receptor dysfunction." (PMID 39483531, 2024). "Ectonucleotide pyrophosphatase/phosphodiesterase family member 1 (ENPP1) was associated with insulin resistance by inhibiting the activity of insulin receptor (IR) and concomitantly preventing downstream signaling." (PMID 38122899, 2024). "Shunting of portal-hypertensive-associated insulin from the portal venous system into the systemic circulation causes hyperinsulinemia, insulin receptor desensitization and insulin downregulation, leading to insulin resistance." (PMID 39040676, 2024). "Serine/threonine residue phosphorylation of insulin receptor substrates (IRS1 Ser307) instead of tyrosine phosphorylation (Tyr612) causes insulin resistance." (PMID 39795155, 2024). "Intraventricular injection of STZ has been demonstrated to induce insulin resistance in the brain and significantly reduce the insulin receptor IRS-2, accompanied by significant memory loss, Aβ deposition and tau phosphorylation." (PMID 38379904, 2024). "Homozygous INSR mutations are typically associated with two syndromes of severe insulin resistance; Donohue syndrome and Rabson-Mendenhall syndrome." (PMID 38461278, 2024). "Insulin resistance is primarily caused by the inability of insulin to effectively activate the insulin receptor substrate (IRS)." (PMID 39518747, 2024). "According to recent research, circulating mannose levels are positively associated with obesity-independent insulin resistance due to mannose’s interference with insulin receptor function or its role in glycation end product." (PMID 38254716, 2024). "It is also suggested that high concentrations of autoantibodies antagonize INSR, causing its inhibition and leading to insulin resistance and hyperglycemia." (PMID 38397072, 2024). "Insulin resistance, in turn, triggers inflammation, oxidative stress, insulin receptor mutations, endoplasmic reticulum stress, and mitochondrial dysfunction, impairing arterial endothelial function and leading to the development of hypertension and diabetes." (PMID 38883798, 2024). "To answer this question, we generated atherosclerosis-prone mice with whole-body insulin resistance secondary to haploinsufficiency of the insulin receptor (IR+/−) deficient in ApoE−/− (IR+/−/ApoE−/−)." (PMID 39401163, 2024). "At the same time, these cytokines disrupt insulin receptor function, causing insulin resistance and hyperinsulinemia." (PMID 39845049, 2024). "Recent studies have reported that insulin resistance is primarily caused by the inability of insulin to effectively activate the insulin receptor substrate (IRS)." (PMID 38818523, 2024). "It has been implicated in the disruption of insulin receptor signaling, thereby promoting insulin resistance and hyperglycemia." (PMID 39707185, 2024). "Rabson-Mendenhall syndrome (RMS) is a rare autosomal, recessive disorder characterized by severe insulin resistance due to mutations in the insulin receptor (INSR) gene." (PMID 38957655, 2024). "Insulin resistance contributes to NAFLD by damaging the insulin receptor signaling, causing the defective inhibition of FFA release from fat cells." (PMID 37894381, 2023). "For example, DNA methylation of the insulin receptor (INSR) gene has been shown to be associated with insulin resistance and type 2 diabetes." (PMID 37445852, 2023). "Mechanistically, insulin resistance is associated with increased serine phosphorylation of the insulin receptor substrate (IRS) mediated by serine/threonine kinases including mTOR and p70S6K." (PMID 36982168, 2023). "It was reported that therapy with oleanolic acid improved insulin sensitivity by increasing the expression of insulin receptor and glucose transporter proteins in HepG2 cells, which is significant because insulin resistance is a hallmark of type 2 DM." (PMID 36983154, 2023).
Insulin resistance (continued). "The disorder of glucose and lipid metabolism caused by insulin resistance is an important factor leading to obesity, and INSR plays an important role in this process." (PMID 36834919, 2023). "Type A insulin resistance syndrome is caused by mutations in the insulin receptor (INSR) gene and results in severe insulin resistance." (PMID 37042492, 2023). "Mutations of the INSR gene result in extreme insulin resistance and dysglycemia because of the dysfunction of INSR." (PMID 37042492, 2023). "Free fatty acids can bring on insulin resistance in several different ways; increased lipid metabolism caused by FFAs is linked to insulin resistance because it inhibits the insulin receptor." (PMID 37241737, 2023). "In at least 50% of PCOS women, insulin resistance appears to be associated with increased serine phosphorylation of the insulin receptor." (PMID 37954695, 2023). "The degradation of INSR induced by high levels of insulin stimulation has also been demonstrated to cause insulin resistance in podocytes." (PMID 37884540, 2023). "Blockage of insulin receptor-related signaling processes is an important cause of insulin resistance." (PMID 38201125, 2023). "Donohue syndrome (DS) is a rare recessively inherited disorder characterized by severe insulin resistance caused by genetic defects affecting the insulin receptor." (PMID 37885901, 2023). "Resistin is induced by genetic factors and several stimuli, leading to the inhibition of insulin receptor signaling, and subsequently causing insulin resistance." (PMID 37763771, 2023). "As reviewed by Yohannes Tsegyie Wondmkun, defective insulin receptor signaling is a major component of obesity-associated insulin resistance in humans." (PMID 36735680, 2023). "This association is partly due to its ability to alter glucose transporter translocation to the plasma membrane, thereby reducing systemic glucose uptake, and partly due to its ability to inhibit pro-insulin receptor cleavage, causing insulin resistance." (PMID 37049394, 2023). "Insulin resistance is associated with dysfunctional insulin receptor signaling, affecting the activity of the downstream Akt kinase." (PMID 37762417, 2023). "A 17-year-old boy (the proband) presented with severe insulin resistance possibly caused by a novel deletion mutation of the B subunit of INSR." (PMID 37042492, 2023). "The UPS is responsible for the degradation of the insulin receptor and the insulin receptor substrate, thereby contributing to insulin resistance and deficiency." (PMID 37895057, 2023). "Type B insulin resistance (TBIR) is a rare, often fulminant form of insulin resistance caused by autoantibodies against the insulin receptor." (PMID 37706022, 2023). "During their chronic scavenging activity, macrophages produce several secretory products that have collateral consequences, including interference with insulin receptor activity, causing insulin resistance." (PMID 37507987, 2023). "High levels of IFN-γ produced by NK cells in response to persistent infection cause insulin resistance by downregulating insulin receptor transcription in myocytes." (PMID 37718435, 2023). "Chronic peripheral hyperinsulinemia can cause brain insulin resistance and defective insulin receptor activity by impairing the blood–brain barrier and insulin transport to the brain." (PMID 36776436, 2023). "This can be particularly relevant in Alzheimer’s disease that is fundamentally associated with insulin resistance, impaired insulin receptor signaling, and dysfunctional glucose metabolism in the brain, which can contribute to the cognitive decline." (PMID 37443733, 2023). "Our genomic investigation allowed the identification of a novel heterozygous pathogenic variant (c.1649C>T, p.Ala550Val) in exon 8 of the INSR gene in patient P10 and in his diabetic father having type A insulin resistance." (PMID 38162681, 2023).
Insulin resistance (continued). "Insulin sensitizers bind allosterically to InsR and sensitize insulin action to alleviate insulin resistance and minimize the hypoglycemia risk." (PMID 35502441, 2022). "For example, ER stress has been shown to be associated with insulin resistance, which was accompanied by a suppression of insulin receptor signaling and serine phosphorylation of insulin receptor substrate-1 (IRS-1), in vivo and in vitro." (PMID 35615361, 2022). "Any functional defect of INSR gene will directly affect the action of insulin and cause insulin resistance, thus leading to the development of T2D." (PMID 35885938, 2022). "Recently it was shown that the dystrophin–glycoprotein complex interacts with the insulin receptor and regulates insulin signalling in skeletal muscle, suggesting that mutations in this complex contribute to the development of insulin resistance and T2D." (PMID 35796564, 2022). "Nonetheless, insulin resistance in DM1 patients is thought to be caused mainly by aberrant production of the fetal isoform of the insulin receptor in adult muscle tissues and by altered post-receptor signaling." (PMID 36362145, 2022). "It is also a crucial component in obesity-linked insulin resistance by inhibiting insulin receptor signaling and the transportation of glucose in the target cells." (PMID 35631100, 2022). "It has been suggested that hyperglycemia causes the progression of insulin resistance through the generation of reactive oxygen species (ROS), which abolish insulin-induced tyrosine autophosphorylation of the insulin receptor." (PMID 35455055, 2022). "The polymorphism rs2059817 and rs1799817 in INSR gene was most widely associated with insulin resistance among PCOS women in various populations." (PMID 35327342, 2022). "IAV studies done with insulin receptor-deficient mice, which mimic human insulin resistance, demonstrated that insulin resistance resulted in reduced immune responses and poor protection against an H1N1 challenge." (PMID 36532060, 2022). "First, knocking out insulin receptor in Glut4-expressing tissues conferred insulin resistance and predisposed mice to defective glucose metabolic homeostasis." (PMID 34801552, 2022). "We have not elucidated the precise mechanism by interactions between TNF-α and the loss of insulin receptor and subsequent insulin resistance." (PMID 35198097, 2022). "It has been shown that the mutations in the insulin receptor gene (INSR) lead to severe insulin resistance in humans." (PMID 34996843, 2022). "In contrast, heterozygous INSR variants in the intracellular β subunit, which are synthesized and interfere with WT receptor function, cause type A insulin resistance." (PMID 34875679, 2022). "Increased ROS levels cause insulin resistance in the peripheral tissues by affecting insulin receptor signal transduction, ultimately resulting in hyperinsulinemia and cell glucose desensitization." (PMID 35711534, 2022). "The abnormalities in INSR splicing and postreceptor signaling are associated with insulin resistance and hyperinsulinaemia." (PMID 36589630, 2022). "Over 33 years since pathogenic mutations in the INSR gene were discovered in people with extreme insulin resistance, more than 25 monogenic disorders that feature insulin resistance disproportionate to body fat mass have been described." (PMID 35618782, 2022). "Studies found a significant loss of insulin receptor mRNA in the substantia nigra pars compacta (SNpc) of patients with PD with increased insulin resistance compared with age-matched controls." (PMID 35164216, 2022). "These substances can affect the insulin receptor's sensitivity and conduction mechanism, leading to insulin resistance, which is recognized to be one of the causes of metabolic syndrome and later makes type 2 diabetes more likely." (PMID 36212053, 2022). "The increased concentration of phosphorylated IRS-1 inhibits the insulin receptor, thus causing insulin resistance." (PMID 36230942, 2022).
Insulin resistance (continued). "There are 23 MMPs expressed in humans, and they have been recently shown to be associated with receptor cleavage of the insulin receptor, leading to insulin resistance and insulin resistance is typically associated with hypertension." (PMID 35742125, 2022). "At the molecular level, insulin resistance is often associated with impaired tyrosine phosphorylation of IRS-1 despite normal activation of the insulin receptor." (PMID 35625574, 2022). "Clozapine administration in animal models of insulin resistance reduced the signaling deficiency for the insulin receptor." (PMID 35615716, 2022). "The first identification of a genetic basis for severe insulin resistance—mutations in the gene encoding the insulin receptor (INSR)—was in 1988, 3 years after sequencing of the INSR gene." (PMID 35618782, 2022). "Mutations in the insulin receptor (IR) gene are associated with metabolic syndromes such as the insulin resistance, which can lead to T2D cardiovascular disorders." (PMID 36589630, 2022). "In other words, their IRAb occupies the insulin-binding domain of the insulin receptor, rendering their endogenous insulin to become ineffective in binding with the insulin receptors and hence causing severe insulin resistance." (PMID 36387920, 2022). "Evidence that the nuclear InsR pathway is functionally involved in conditions associated with insulin resistance was provided by animal experiments showing a reduction in the levels of chromatin-bound InsR in an ob/ob mouse, a model of insulin resistance." (PMID 33918477, 2021). "These alterations in insulin receptor signalling pathways in response to short-term exposure to low doses of BPA provide insight into the development of peripheral insulin resistance, a key hallmark of T2DM." (PMID 33467592, 2021). "Deletion of the insulin receptor (IR) in mice is known to cause perinatal lethality due to diabetic ketoacidosis, and mice heterozygous for Ir display mild insulin resistance and compensatory increases in β-cell mass." (PMID 34568323, 2021). "High levels of insulin can cause insulin receptor degradation and drive early podocyte insulin resistance, and both the insulin receptor and nephrin are needed for full insulin sensitivity of podocytes." (PMID 33628839, 2021). "GM3 would cause insulin resistance, by reduction of insulin receptor presentation on fat cell surface due to changes in composition of lipid rafts." (PMID 35097004, 2021). "Two miRNAs, miR-1983 and miR-7, have emerged as miRNAs associated with neuronal insulin resistance that directly target the InsR." (PMID 34831343, 2021). "Since hepatic insulin resistance caused by the DAG–PKCε pathway occurs at the level of phosphorylation of the insulin receptor, it is reasonable to assume that insulin-independent DNL occurs in cases of MAFLD with nutrient oversupply." (PMID 33923817, 2021). "This relation is associated with insulin deficiency or dysfunction of insulin receptor signaling due to insulin resistance." (PMID 34577866, 2021). "There is an underlying association between galectin-3 and insulin resistance in that galectin-3 directly binds the insulin receptor, which inhibits downstream insulin receptor signaling." (PMID 35008499, 2021). "IGF-1R can form hybrid receptors with insulin receptor (IR), and insulin resistance is one of risk factors of neurodegenerative diseases." (PMID 34445359, 2021). "Mg deficiency was also found to be associated with insulin resistance in obesity due to modulation of insulin receptor phosphorylation as well as insulin secretion." (PMID 34064348, 2021). "The association between Zn and insulin resistance can be partially explained by Zn ions’ inhibition of protein tyrosine phosphatase 1B, a crucial regulator of the active phosphorylation form of the insulin receptor." (PMID 34066324, 2021).
Insulin resistance (continued). "The 1970s saw the identification by Jeffrey Flier of anti-insulin receptor antibodies as the cause of severe insulin resistance in identified patients with an unusual diabetic syndrome." (PMID 34717951, 2021). "PD-associated systemic inflammation can inhibit the insulin receptor, promoting insulin resistance [G]." (PMID 34776994, 2021). "Insulin resistance is considered to be an adverse metabolic and a key risk factor for developing cardiovascular diseases, and insulin receptor substrates (IRS) are key modulators of insulin signal transduction pathways in the heart." (PMID 33668039, 2021). "With the idea of being able to delve into the mechanisms involved in insulin resistance, different experimental models have been developed in tissue-specific insulin receptor-deficient mice using Cre-loxP technology." (PMID 34440804, 2021). "Severe insulin resistance caused by loss-of-function mutations in the insulin receptor (INSR) gene comprises a wide phenotypic spectrum, including Donohue syndrome (DS), Rabson-Mendenhall syndrome (RMS) and type A insulin resistance (type A-IR)." (PMID 33995269, 2021). "It was shown recently that membrane-bound DAG caused hepatic insulin resistance through PKC-mediated insulin receptor phosphorylation." (PMID 33772019, 2021). "mTOR-S6K1-mediated phosphorylation of IRS-1, and degradation of IRS-1 and InsR via the proteasomal or lysosomal pathway, respectively, were implicated in the mechanism of insulin-induced insulin resistance in these NPY/AgRP-expressing cells." (PMID 34831343, 2021). "Though, several factors contribute to the onset and aggravation of insulin resistance, numerous studies have implicated the loss of function of insulin receptor substrates (IRS) as the mechanistic link to the dysregulation of insulin signaling." (PMID 33953863, 2021). "Multiple defects in the insulin receptor downstream cascade especially the IRS/PI3K pathway have been linked to insulin resistance and currently represent a promising druggable target for antidiabetic agents." (PMID 33953863, 2021). "In LFD mice, IH‐induced hyperinsulinemia and systemic insulin resistance that were associated with increased phosphorylations of cardiac insulin receptor and Akt on Tyr1150 and Ser473 residues, respectively." (PMID 33682327, 2021). "OS can also cause insulin receptor damage, interfere with the insulin signal pathway of insulin binding with insulin receptor, and cause insulin resistance." (PMID 34526965, 2021). "Leprechaunism, type A insulin resistance and Rabson-Mandenhall are the three rare syndromes characterized by mutations in the insulin receptor gene." (PMID 33555509, 2021). "Enhanced GM3 lipid raft content disturbs insulin receptor function causing insulin resistance and finally diabetes type 245." (PMID 32680999, 2020). "INSR mutations are associated with severe insulin resistance (IR) phenotypes, such as Rabson-Mendenhall, Donohue and type A IR syndrome." (PMID 31989990, 2020). "Phosphorylation of Irs1 prevents its association with the insulin receptor and thus can inhibit insulin action and result in insulin resistance." (PMID 33330474, 2020). "The disorder is autosomal recessively inherited and characterized by extreme insulin resistance due to mutations in the insulin receptor (INSR) gene." (PMID 31840185, 2020). "In GSAT, global DNA methylation was correlated with higher systemic inflammation and INSR methylation was associated with insulin resistance in black women." (PMID 33133129, 2020). "A key negative regulator of insulin signalling is protein tyrosine phosphatase 1B (PTP1B) that causes dephosphorylation of activated insulin receptor and induction of insulin resistance." (PMID 32042410, 2020). "There is evidence that GM3 regulates insulin signaling by lateral association with InsR, and thereby triggers development of insulin resistance." (PMID 32731387, 2020).